ETV6 (ETS variant transcription factor 6)
Diseases named in the same sentence as ETV6 in open-access papers (continued):
Sharing a sentence is not in itself a finding about the gene and the disease.
leukemia (continued). "Etv6 and Runx1 are known leukemic regulators, and Suz12 and Ezh2 are core members of the Polycomb repressive complex 2 (PRC2), whose activities have been shown to be essential for MLL-AF9 driven leukemia." (PMID 25517911, 2014). "Increased quiescence of ETV6::RUNX1+ preleukemic cells is in keeping with our previous detection of these cells in cord blood of approximately 5% of healthy newborns, offering a potential explanation for prolonged latency periods of ETV6::RUNX1+ leukemia, which can extend up to 14 years." (PMID 40177616, 2025). "ETV6/RUNX1 (E/R) (also known as TEL/AML1) is the most frequent gene fusion in childhood acute lymphoblastic leukemia (ALL) and also most likely the crucial factor for disease initiation; its role in leukemia propagation and maintenance, however, remains largely elusive." (PMID 22028862, 2011). "ETV6::RUNX1, the most common oncogenic fusion in pediatric B cell precursor acute lymphoblastic leukemia (BCP‐ALL), induces a clinically silent preleukemic state that can persist in carriers for over a decade and may progress to overt leukemia upon acquisition of secondary lesions." (PMID 40177616, 2025). "Although there is evidence that some leukemic translocations, such as ETV6/RUNX1, occur at substantially higher rates in utero than the rate of overt leukemia, there may be translocations whose frequency of in utero initiation is near that of the specific leukemia subtype to which they give rise." (PMID 33968846, 2021). "In leukaemia BM blast cells of mice with MLL-AF9-induced AML, the expression of Crtc1, Flt3 and Mycbp, but not Etv6, was significantly downregulated by co-expressed miR-22 (but not by miR-22 mutant)." (PMID 27116251, 2016).
acute lymphoblastic leukemia (71 papers, 2010 to 2026). Leukemia with an acute onset, characterized by the presence of lymphoblasts in the bone marrow and the peripheral blood. "Two of the genes associated with the MMR pathway, MSH6 and SETD2, were among the genes found to be frequently mutated in relapsed or therapy resistant ETV6/RUNX1 acute lymphoblastic leukemia (ALL)." (PMID 36672189, 2023). "Among the pediatric/AYA cohort, the ETV6::RUNX1 fusion typically associated with a favorable outcome in acute lymphoblastic leukemia was most frequent." (PMID 37686670, 2023). "The forming of ETV6-NUFIP1 fusion gene has been reported as a potential cause of acute lymphoblastic leukemia in Mexico." (PMID 34863153, 2021). "More recently, whole genome sequencing studies of acute lymphoblastic leukemia (ALL) patients carrying the ETV6/RUNX1 translocation have further implicated broken RSSs in the generation of chromosome alterations." (PMID 30905508, 2019). "Genetic fusions between Jak2 and the Translocation-Ets-leukemia (Tel/ETV6) gene that constitutively activate Jak appear to be causative for some cases of chronic myeloid leukemias and acute lymphoblastic leukemia." (PMID 30558204, 2018). "While ETV6::RUNX1-positive acute lymphoblastic leukemia (ALL) is generally associated with favorable outcomes, a subset of patients experience relapse despite receiving standard therapy, underscoring the need for early biomarkers to identify high-risk subgroups." (PMID 42213136, 2026). "Somatic mutations affecting ETV6 often occur in acute lymphoblastic leukemia (ALL), the most common childhood malignancy." (PMID 26102509, 2015). "Acute lymphoblastic leukemia harboring the ETV6::ABL1 fusion constitutes a rare but clinically relevant subtype, typically associated with poor prognosis." (PMID 41228238, 2025). "Several other recurrent alterations, such as ETV6::RUNX1, KMT2A rearrangements, and high hyperdiploidy in childhood acute lymphoblastic leukemia, are associated with prognosis and treatment decisions." (PMID 40725438, 2025). "Further in 2019, METTL3 and METTL14 expression was reported to be downregulated in ETV6/RUNX1-positive acute lymphoblastic leukemia as compared to the controls." (PMID 39600630, 2024). "For example, the RUNX l gene is the second gene found to be rearranged with ETV6 after PDGFRB, and the ETV6 / RUNXl fusion gene is considered the most common fusion gene in early childhood acute lymphoblastic leukemia." (PMID 39634885, 2024). "ETV6::RUNX1 is a genetic rearrangement of good prognosis in children with acute lymphoblastic leukemia (ALL)." (PMID 35685921, 2022). "METTL3 and METTL14 expression was reported to be downregulated in pediatric acute lymphoblastic leukemia (ALL) with ETV6/RUNX1 gene rearrangement." (PMID 33922187, 2021). "This study was aimed to explore the METTL3 and METTL14 expressions in children with ETV6/RUNX1(E/R)‐positive acute lymphoblastic leukemia (ALL) and investigate the relation between the METTL3 and METTL14 expressions with clinical features." (PMID 31429529, 2019). "Evaluation for germline alterations of ETV6 is therefore warranted in families with acute lymphoblastic leukemia, particularly when there is preceding evidence of thrombocytopenia." (PMID 26102509, 2015). "A high resolution 244K array-based Comparative Genomic Hybridization (array-CGH) was used to study eleven ETV6/RUNX1-positive childhood acute lymphoblastic leukemia (ALL) patients." (PMID 23151340, 2012). "ETV6::RUNX1-positive pediatric acute lymphoblastic leukemia frequently has a prenatal origin and follows a two-hit model: a first somatic alteration leads to the formation of the oncogenic fusion gene ETV6::RUNX1 and the generation of a preleukemic clone in utero." (PMID 40243620, 2025). "Recent trials show 5-year survival rates >95% for ETV6::RUNX1 Acute Lymphoblastic Leukemia (ALL)." (PMID 38844578, 2024). "ETV6/RUNX1 (E/R) is the most common fusion gene in childhood acute lymphoblastic leukemia." (PMID 24240203, 2014).
acute lymphoblastic leukemia (continued). "ETV6::RUNX1 is the second most frequent form of B cell acute lymphoblastic leukemia (B-ALL) in childhood." (PMID 40634509, 2025). "ETV6/RUNX1 gene fusion is the most common chromosomal translocation abnormality occurred in pediatric B-cell acute lymphoblastic leukemia (B-ALL)." (PMID 34101758, 2021). "Pediatric B-cell precursor acute lymphoblastic leukemia (BCP-ALL) is associated with a high frequency of copy number alterations (CNAs) in IKZF1, EBF1, PAX5, CDKN2A/B, RB1, BTG1, ETV6, and/or the PAR1 region (henceforth: B-cell development genes)." (PMID 30874617, 2019). "Phosphatase of regenerating liver-3 (PRL-3/PTP4A3) is upregulated in multiple cancers, including BCR-ABL1- and ETV6-RUNX-positive acute lymphoblastic leukemia (ALL)." (PMID 29423065, 2018). "In childhood B-precursor acute lymphoblastic leukemia (B-ALL), the ETV6/RUNX1 fusion transcript is considered to have an excellent outcome." (PMID 30115129, 2018). "A clinical follow-up was conducted on 137 B-ALL children with positive genes (59 cases of ETV6/RUNX1 positivity, 22 cases of E2A/PBX1 positivity, 25 cases of MLL positivity, and 19 cases of BCR/ABL positivity) among 302 children with acute lymphoblastic leukemia." (PMID 41195225, 2025). "To date, ETV6::ABL1 has been reported on various hematological malignancies, including B/T-acute lymphoblastic leukemia, acute myeloid leukemia (AML), and myeloproliferative neoplasm (MPN)." (PMID 39066837, 2024). "Proband IV‐3, a child diagnosed with B‐acute lymphoblastic leukemia (B‐ALL) at 8 years old, tested positive for ETV6::RUNX1 fusion." (PMID 38970307, 2024). "Acute lymphoblastic leukemia (ALL) is the most common pediatric hematological malignancy, with ETV6::RUNX1 being the most prevalent translocation whose exact pathogenesis remains unclear." (PMID 37670323, 2023). "ETV6/RUNX1 (E/R) is the most common fusion gene in childhood acute lymphoblastic leukemia (ALL)." (PMID 28418909, 2017). "Fourth, we performed a 4-year follow-up in which none of the ETV6::RUNX1-positive newborns have been diagnosed with acute lymphoblastic leukemia." (PMID 40243620, 2025). "Moreover, a fusion of ETV6 with the BAZ2A intron sequence generated by a cytogenetically cryptic rearrangement between 12p13 and 12q13 occurred in a pediatric case of pre-B acute lymphoblastic leukemia (ALL), which encodes a truncated form of ETV6 that leads to a pathogenic effect." (PMID 34736517, 2021). "In ETV6-Runx1 negative B precursor acute lymphoblastic leukemia (ALL), aberrant expression of ZNF423 induced by epigenetic deregulation inhibits EBF target genes and leads to B cell maturation arrest associated with poor outcome." (PMID 29867779, 2018). "For example, the ETS gene ETV6 is fused with different partner genes by specific translocations in lymphoblastic and myeloid acute leukemias, and NKL homeobox gene NKX2-5 is aberrantly activated via juxtaposition to an enhancer region of BCL11B in T-cell acute lymphoblastic leukemia (T-ALL)." (PMID 34768865, 2021).
acute myeloid leukemia (51 papers, 2007 to 2026). Acute myeloid leukemia (AML) is a group of neoplasms arising from precursor cells committed to the myeloid cell-line differentiation. "ANKRD26-related thrombocytopenia (ANKRD26-RT), ETV6-related thrombocytopenia (ETV6-RT), and familial platelet disorder predisposing to acute myeloid leukemia (FPD/AML) are three HT linked to specific predispositions to hematological malignancies." (PMID 41167018, 2025). "ETV6 translocations in acute myeloid leukemias have been described as isolated or associated with a variety of translocations, notably translocations involving NUP98 and NUP214 genes." (PMID 37601839, 2023). "ETV6‐RT has an overall 30% risk for hematologic malignancies—including B‐cell acute lymphoblastic leukemia, acute myeloid leukemia, and myelodysplastic syndrome." (PMID 37405044, 2023). "ETV6::NTRK3 fusion is also reported in acute myelogenous leukemia, chronic eosinophilic leukemia, inflammatory myofibroblastic tumor, pediatric high-grade glioma, and metastatic colorectal carcinoma." (PMID 38390852, 2024). "Inactivation by the mutation or deletion of ETV6, RUNX1, and GATA3 has also been described in patients with Acute Myeloid Leukemia (AML) and correlates with poor outcomes in ETP-ALL." (PMID 35626079, 2022). "For instance, Patient 4, a 19-year-old male with a history of longstanding unexplained thrombocytopenia and learning disability, developed acute myeloid leukemia and was suspected to carry a pathogenic variant in RUNX1,ETV6 or ANKRD26." (PMID 28104920, 2017). "To evaluate the impact of the leukemic fusion genes on the course of an adenoviral infection, we created stable B cell lines expressing either the RUNX1 fusion gene commonly associate with ALL (ETV6/RUNX1), or the RUNX1 fusion gene commonly associated with acute myeloid leukemia (RUNX1/MTG8)." (PMID 41497616, 2025). "In addition to the 42-base-pair stretch, the fusion found in congenital fibrosarcoma contains ETV6 exons 1–5 versus 1–4 that are seen in EN fusions found in acute myeloid leukemia (AML)." (PMID 31551508, 2019). "For hematological malignancies, hereditary predisposition was first identified in chronic lymphocytic leukemia (CLL) and acute myeloid leukemia (AML), which has led to the identification of several germline mutations, such as RUNX1, CEBPA, GATA2, ANKRD26, DDX41 and ETV6 mutations." (PMID 36998465, 2023). "ETV6, RUNX1, and GATA3, described also in acute myeloid leukemia, are deleted or inactivated in ETP-ALL, and correlate with poor outcome: ETV6 (12p13) mutations account for ~25% of ETP-ALL, whilst RUNX1 (21q22), and GATA3 (10p14) mutations are less common." (PMID 32185137, 2020). "Interestingly, it was reported that METTL3 mRNA and protein expression was increased in acute myeloid leukemia (AML) cells compared to healthy hematopoietic stem and progenitor cells, and a higher expression was reported in pediatric ALL ETV6/RUNX1-positive patients when compared to controls." (PMID 36428851, 2022).
Thrombocytopenia (33 papers, 2013 to 2026). A reduction in the number of circulating thrombocytes. "ETV6-related thrombocytopenia (ETV6-RT) is an inherited platelet disorder caused by germline ETV6 variants." (PMID 42049211, 2026). "Background/Objectives: ETV6-related thrombocytopenia (ETV6-RT) is a rare autosomal dominant disorder characterized by mild thrombocytopenia since birth and an increased predisposition to hematologic malignancies." (PMID 40004441, 2025). "Since its first description in 2015, many novel mutations of ETV6 gene were identified in patients with thrombocytopenia and/or acute leukemia, mostly clustered in the gene region encoding the ETS domain." (PMID 40004441, 2025). "Patients with germline ETV6 mutations similarly present with thrombocytopenia and mucosal bleeding, though some patients also have anemia and/or neutropenia at presentation." (PMID 38473358, 2024). "For example, ETV6 (ETS Variant Transcription Factor 6) is a transcriptional repressor implicated in dominantly inherited thrombocytopenia." (PMID 38228368, 2024). "For example, germline variants in RUNX1, ANKRD26, and ETV6 all predispose to thrombocytopenia and hematologic malignancies." (PMID 38203823, 2024). "Mutations in the genes ANKRD26, RUNX1, and ETV6 cause three clinically overlapping thrombocytopenias characterized by a predisposition to hematological neoplasms." (PMID 39791724, 2024). "RUNX1 mutations are associated with familial platelet disorder (FPD) with a predisposition to AML, while ANKRD26 and ETV6 mutations are associated with inherited thrombocytopenia and a predisposition to developing MDS and AML." (PMID 38473358, 2024). "ETV6 variants (e.g., R369Q) in heterozygosity have also been shown to drive thrombocytopenia in iPSCs, with more, but less responsive megakaryocytes that are deficient in platelet formation, leading to fewer platelets." (PMID 37377909, 2023). "Genetic sequencing revealed a rare variant in ETS Variant Transcription Factor 6, which is associated with inherited thrombocytopenia with predisposition to hematologic malignancy." (PMID 37405044, 2023). "In conditional knockout mice, thrombocytopenia is observed as the primary phenotype due to an increase in megakaryocytic colony forming cells implying a loss of ETV6 results in a terminal defect in megakaryocyte maturation." (PMID 37377909, 2023). "Familial testing reveals a rare ETV6 variant likely causing inherited thrombocytopenia in this family." (PMID 37405044, 2023). "Pathogenic germline variants in genes encoding the prominent transcription factors RUNX1, GATA1, FLI1, GFI1b, and ETV6 are known to cause thrombocytopenias, associated with large and normal platelet size, respectively." (PMID 36231035, 2022). "Aberrant gene expression in MKs results in defective proplatelet formation, underpinning the thrombocytopenia observed in patients with germline mutations in ETV6." (PMID 32841218, 2020). "We and others have identified heterozygous germline ETV6 mutations as the cause for dominantly inherited thrombocytopenia in several families." (PMID 32841218, 2020). "Despite these recent advancements in the field, the precise molecular mechanisms underpinning thrombocytopenia and cancer predisposition in patients with ETV6 mutations have yet to be defined." (PMID 32841218, 2020). "Mutations in transcriptional regulators, such as RUNX1 or ETV6, hit Mk maturation and perturb hematopoietic precursors leading to thrombocytopenia, impaired platelet function, and increased risk of clonal hematopoiesis." (PMID 32079152, 2020). "In summary, our genetic and molecular studies in patient-derived PBMCs demonstrated a potential mechanism for ETV6-mediated thrombocytopenia and predisposition to hematopoietic malignancies." (PMID 32841218, 2020). "In both kindreds ETV6 mutations were inherited in an autosomal dominant manner with variable expression of thrombocytopenia and/or ALL." (PMID 26102509, 2015).
Thrombocytopenia (continued). "Recent studies identified ETV6 germline variants associated with rare hereditary thrombocytopenia and a plausible increased susceptibility to hematologic malignancies, including ALL." (PMID 26522332, 2015). "In the 3 reports of germline ETV6 mutations to date (including the current series), a mixed phenotype of thrombocytopenia and ALL is observed." (PMID 26102509, 2015). "Patients with thrombocytopenia 5, an autosomal dominant disorder of thrombocytopenia with bleeding tendency, usually present in childhood and have been found to have germline variants in ETV6." (PMID 38203823, 2024). "Furthermore, a relationship between heterozygous germline ETV6 mutations to dominantly inherited thrombocytopenia and predisposition to hematologic malignancies was defined." (PMID 36766699, 2023). "A next‐generation sequencing (NGS) based panel of genes associated with inherited thrombocytopenia was performed at Versiti Diagnostic Laboratories in a blood sample of patient B. The germline heterozygous ETV6 c.1085A>G (p.Asp362Gly) missense variant was identified." (PMID 37405044, 2023). "Finally, a heterozygous nonsense variant (R359*) of ETV6 was identified in a 28-year-old male, which was clinically consistent with a previous history of thrombocytopenia." (PMID 38137719, 2023). "Interestingly, germline pathogenic variants in both TFs co-segregate with autosomal dominant bleeding disorders (i.e., mild thrombocytopenia), although ETV6 also presents a HM risk in ~30% of carriers while FLI1 is most commonly autosomal recessive." (PMID 37377909, 2023). "Despite the well-defined association between germline mutations in ETV6 and thrombocytopenia, the transcriptional role of ETV6 in human MK maturation and platelet production is still unknown." (PMID 32841218, 2020). "Additionally, mutations in ANKRD26, RUNX1, and ETV6 may predispose patients to thrombocytopenia by disrupting normal megakaryocyte function, significantly affecting platelet production." (PMID 40757104, 2025). "Furthermore, this study emphasizes the clinical vulnerability of individuals with germline RUNX1-FPDMM—as well as those with other thrombocytopenia-associated predispositions such as ETV6 or ANKRD26—and underscores the need for dedicated healthcare infrastructure." (PMID 41458504, 2025). "Since its first description, novel variants of ETV6, often of uncertain significance (VUS), and mostly located in the ETS domain, emerged from individuals with suspected inherited thrombocytopenia." (PMID 40004441, 2025). "At least 15 different heterozygous germline mutations of ETV6, mainly missense amino acid substitutions affecting the ETS domain, have been associated with thrombocytopenia." (PMID 39791724, 2024). "ETV6-related thrombocytopenia belongs to a group of a few autosomal dominant forms of inherited thrombocytopenia without platelet macrocytosis." (PMID 36766699, 2023). "Distinguishing ETV6‐related thrombocytopenia (ETV6‐RT) from other etiologies is important, given its associated risk of malignancy, and requires genetic testing for diagnostic confirmation." (PMID 37405044, 2023). "Variants of ANKRD26 and of transcription factors ETV6 and RUNX1, which are associated with autosomal dominant (AD) inherited disorders, represent almost one-quarter of inherited thrombocytopenia cases." (PMID 36430862, 2022). "MDS and AML are reported in about 40% of patients with RUNX1 germline mutations and in 8% of patients with ANKRD26 related thrombocytopenia, whereas 23% of the 73 patients with ETV6 familial thrombocytopenia described so far had hematological malignancies." (PMID 33802366, 2021). "Once a diagnosis of inherited thrombocytopenia with germline mutation in RUNX1, ANKRD26, or ETV6 is established, close and long-term surveillance is mandatory given the lifelong increased risk of developing hematologic malignancies." (PMID 33802366, 2021).